SNORD115-15 (small nucleolar RNA, C/D box 115-15)
Synonyms: HBII-52-15
Gene: Small nucleolar RNA gene on chromosome 15 (25,197,576 to 25,197,656, forward strand). Ensembl gene ENSG00000201679.
Gene Ontology:
Biological process: RNA processing
Cellular component: nucleolus
Homologues: Orthologues: macaque SNORD115 (99% identical), chimpanzee SNORD115 (98% identical). Paralogues in human: SNORD115-42 (100% identical), SNORD115-12 (99% identical), SNORD115-4 (99% identical), SNORD115-6 (99% identical), SNORD115-9 (99% identical), SNORD115-10 (98% identical), SNORD115-11 (98% identical), SNORD115-13 (98% identical), SNORD115-14 (98% identical), SNORD115-20 (98% identical), SNORD115-29 (98% identical), SNORD115-34 (98% identical), and 37 more.